BRCA2 (BRCA2 DNA repair associated)
Diseases named in the same sentence as BRCA2 in open-access papers (continued):
Sharing a sentence is not in itself a finding about the gene and the disease.
tumor (continued). "Several studies have shown that BRCA2-mutant tumors have increased the susceptibility to immune checkpoint blockade due to its effects on the tumor immune microenvironment." (PMID 36556296, 2022). "Almost 41% of somatic mutations in the BRCA2 tumor suppressor are truncating mutations, most of which result in loss of multiple BRCA2 functional domains." (PMID 35158934, 2022). "Clinical integration of functional assays into the genetic counseling setting is an important goal but should be undertaken with caution until we fully understand how specific variants impact the tumor suppressor functions of BRCA2." (PMID 36098506, 2022). "When her tumor later developed platinum resistance, it was found to have a reversion mutation that restored BRCA2 functionality." (PMID 36418296, 2022). "In the other patient, bearing the germline BRCA2 c.4284dupT p.(Gln1429Serfs*9) variant, tumour testing on relapsing OC tissue showed the large BRCA2 deletion p.(Leu1334_Asn1742del) encompassing the germline variant." (PMID 35463374, 2022). "Discordant tumor LOH status was more common in BRCA2 mutation carriers, likely due to the lower prevalence of LOH within ER+ breast cancers." (PMID 36344544, 2022). "While our study concurs with BRCA2-/- in hyper-deleted tumours (3/5), here we report further association with SPOP mutation." (PMID 36045381, 2022). "We did not observe differences in SPOP mutation or CHD1 loss frequency by tumor BRCA2 status, although these genes have been implicated in impaired HR repair." (PMID 35715489, 2022). "The highest proportion of lymph node involvement was found in BRCA2 mutation carriers with a pT1c tumor (Online Resource 1)." (PMID 35507134, 2022). "BRCAness is the presence of a defect in the homologous recombination repair of tumor cells mimicking the loss of BRCA1 or BRCA2, as well as germline mutations." (PMID 36613648, 2022). "The aim of this study was to establish a uniform procedure for the detection and interpretation of BRCA1 and BRCA2 alterations in different BRCA associated tumor diseases and to facilitate routine diagnostics." (PMID 35251494, 2022). "Here, we evaluated the potential of pyridostatin in eliminating BRCA2‐deficient xenograft tumours in vivo." (PMID 35107878, 2022). "The correlation between BRCA2 mutations and OS remained significant after controlling for tumor type and TMB (HR 0.50, 95% CI 0.30 – 0.83, p = 0.008)." (PMID 34067105, 2021). "Tumor cells with mutation in BRCA1 or BRCA2 genes exhibit defective HR (referred to as BRCAness phenotype) and are pronounceably hypersensitive to ATM and PARP inhibition." (PMID 34718714, 2021). "When RAD52 is knocked out in BRCA1- or BRCA2-deficient tumor cells, HRR frequency is significantly reduced." (PMID 34484285, 2021). "AA patients with pathogenic variants in BRCA2 or PALB2 were 11 times more likely to be diagnosed with TNBC versus another tumor subtype than were EA patients with pathogenic variants in either of these genes (P = 0.001)." (PMID 33479248, 2021). "Tumor formation in BRCA2 mutation carriers generally requires the inactivation of the wild-type allele, often detected by a loss of heterozygosity (LOH)." (PMID 34359619, 2021). "Of the 179 known BC susceptibility SNPs identified through GWAS in the general population, only 10 showed evidence of interaction with BRCA1 or BRCA2 mutation carrier status after taking the tumour ER-status into account." (PMID 33597508, 2021). "The tumors derived from such carriers exhibit loss of heterozygosity, resulting in the loss of the remaining wild-type allele, suggesting that a single functional allele of BRCA2 is sufficient to suppress any tumor development." (PMID 34359565, 2021).
tumor (continued). "Cells deficient in RAD51-mediated HDR through the inactivation of tumor suppressor genes like BRCA1 or BRCA2 exhibit hypersensitivity to poly-ADP ribose polymerase 1 (PARP1) inhibitors." (PMID 33662256, 2021). "Retrospective studies have correlated BRCA1 and BRCA2 mutations, higher tumor mutation burden and infiltration by T cells with improved survival in HGSOC,36, 37 and BRCA2 mutations were found to be enriched among long‐term responders to PARP inhibition." (PMID 33811746, 2021). "In the third case with a BRCA2 frameshift mutation (c.8537_8538delAG p.(Glu2846fs)) only resequencing with newly extracted tumor DNA detected the germline mutation." (PMID 34202525, 2021). "Collectively, these findings suggest that excess adiposity drives inflammation and local estrogen production, which ultimately promotes tumor growth in hyperadipose individuals with DNA repair insufficiency owing to germline BRCA1 or BRCA2 mutations." (PMID 33649363, 2021). "Tumours of these patients almost universally lose both functional copies of the BRCA1 or BRCA2 gene, either by loss of heterozygosity (LOH) of the wild-type allele or, more rarely, by the acquisition of a somatic mutation in the wild-type locus." (PMID 35008208, 2021). "Of the 14 patients with BRCA1/BRCA2 somatic variants identified in tumor samples, two were from the naive treatment group (OC04 and OC28)." (PMID 34660321, 2021). "The canine BRCA2 is a tumor suppressor gene which encodes the BRCA2 protein, involved in DNA repair through interaction with RAD51 recombinase." (PMID 34680380, 2021). "This cohort study examines the association of BRCA1 and BRCA2 with tumor mutation burden and response to immune checkpoint inhibitors." (PMID 33961040, 2021). "In support of BRCA2 functioning as a tumor suppressor via a role in DNA repair/maintenance of genetic stability, tumors with mutations in BRCA2 typically display a type 3 base substitution mutation signature." (PMID 34356050, 2021). "The clinical significance of OC-IS30 was tested in the external OV-TCGA dataset containing 312 HGSCs annotated in term of clinical and molecular finding (Stage, Overall Survival, mutational status of BRCA1 and BRCA2 genes, and tumor mutational burden (TMB)." (PMID 34220848, 2021). "Among the germline mutations, BRCA1 and BRCA2 tumor suppression genes are inherited in an autosomal dominant manner with incomplete penetrance." (PMID 34884434, 2021). "The focus of PARP inhibitors (PARPis) to date has been on BRCA1 and BRCA2 mutated tumours, with clinical benefits seen in patients with mutations in these DNA repair genes such as ovarian, breast, prostate and pancreatic cancers." (PMID 34445211, 2021). "For example, significant expression deficiency or LOH of the BRCA1 or BRCA2 genes can often be masked by the presence of these genes in the normal cells in the tumor biopsy." (PMID 34145376, 2021). "In summary, PALB2 tumours show the homologous recombination deficiencies characteristic of BRCA1 and BRCA2 tumours, and highlight the potential clinical relevance of PALB2 mutational status in guiding therapeutic choices." (PMID 33893315, 2021). "A recent study proposed that loss of PARG activity is a possible mechanism for PARPi resistance in BRCA2 deficient tumours." (PMID 33674744, 2021). "Accordingly, based on complementary mechanisms of action, the effects of combining ABBV-176 with the PARP inhibitor ABT-888 (Veliparib) were investigated in the CTG-0670 TNB BRCA1 deficient, BRCA2 mutant PDX tumor models." (PMID 34107902, 2021). "The last patient had a tumor with two variants (BRCA2 p.Leu1620Phe and RAD51D p.Asp110Asn) predicted to be deleterious, but we were unable to ascertain which one was responsible for the response to treatment." (PMID 34206535, 2021). "At this time, in tumor cells, replication stress and DNA damage tolerance will allow the cells to survive the loss of BRCA2 and further stimulate the cell’s tumorigenesis potential." (PMID 33414393, 2021).
tumor (continued). "A correlation between the variant localization in the BCCRs and OCCRs of BRCA2 and type of tumor was observed in 16 BC and seven OC patients." (PMID 34178674, 2021). "We found that some modules specifically associated with the clinical characteristics of BRCA2-MUT BC were related to tumor metabolism, cell migration, and other biological functions, and most candidate genes were also expressed in TNBC." (PMID 34733851, 2021). "As a consequence, the combination of radiotherapy, which is local, local hyperthermia and Olaparib, are expected to cause minimal side effects, as only tumor cells have ineffective BRCA2, which are the main target of Olaparib." (PMID 33926008, 2021). "This study makes the important observation that tumors from patients with BRCA2 mutations had increased PD‐L1 mRNA expression and a higher percentage of PD‐L1 protein expression in tumor‐associated ICs compared to patients with BRCA1 mutations." (PMID 33811746, 2021). "Several poly (adenosine diphosphate-ribose) polymerase (PARP) inhibitors are now in clinical use for tumours with defects in BReast CAncer genes BRCA1 or BRCA2 that result in deficient homologous recombination repair (HRR)." (PMID 34445211, 2021). "The Nagel dataset had too few BRCA2-associated tumours to reliably estimate transcriptome-wide expression variability." (PMID 34287743, 2021). "Recent evidence in mouse models of breast and colorectal cancer, suggest that BRCA2-deficient tumours are more susceptible to ICIs than BRCA1-deficient tumour." (PMID 35096825, 2021). "PARP, BRCA1 and BRCA2 are components required for efficient DNA repair, and therefore, tumour cells that already harbour a BRCA1 or BRCA2 mutation will have increased sensitivity to PARP inhibitor therapy." (PMID 34254730, 2021). "Further studies are warranted to examine the functional effect of specific germline BRCA2 mutations on the activity of immune cells as well as the impact of BRCA2 mutations on the immunogenicity of tumor cells." (PMID 34446728, 2021). "PALB2 is a tumor suppressor gene which encodes a protein that stabilizes BRCA2 and allows to scaffold the molecular BRCA1-PALB2-BRCA2 complex at double-stranded breaks (DSBs) to prevent cells from accumulating DNA damage." (PMID 34084283, 2021). "It is noteworthy here that the normal allele of BRCA2 can also be inactivated in various tumor types by epigenetic DNA modifications, such as promoter hypermethylation." (PMID 34356050, 2021). "Taken together, our results, support the existing body of literature characterizing BRCA1 and BRCA2 mutations as predictive of chemo‐response and potentially associated with high tumor immune cell infiltration and PD‐L1 IHC expression." (PMID 33811746, 2021). "As our results show, we detected 77–78% mutated T alleles instead of G in the nucleotide position 7795 in FFPE tumor tissue blocks, suggesting that the majority of the cells within the tumor lost their wild-type BRCA2 alleles." (PMID 34068254, 2021). "The generation of pseudo-reversion mutations in BRCA2-deficient tumors reflects tumor evolution under selection." (PMID 34440403, 2021). "While BRCA1 and BRCA2 deficient tumours are associated with increased immune infiltrates, rates of response to ICI are low." (PMID 35096825, 2021). "The presence of these mutant cells is unexpected since the BRCA2 homozygous mutation was known to be lethal, except for the case of loss of heterozygosity within the tumor." (PMID 34068254, 2021). "The first most clinically relevant application of synthetic lethality is the use of PARP inhibitors in BRCA1‐ or BRCA2‐deficient tumours." (PMID 34254730, 2021).
tumor (continued). "This inhibition of PARG then led to an increase in the autoPARylation of PARP1, which was consistent with the loss of PARG restoring the PAR formation on PARP1 that conferred resistance to PARP inhibition in BRCA2-deficient tumor cells." (PMID 32483468, 2020). "To verify the role of BRCA2 deficiency in tumor development, we generated Villin-Cre+; Brca2fl/fl mice to achieve Brca2 deletion in gastrointestinal epithelial cells." (PMID 32980867, 2020). "BCCIP is an important BRCA2 cofactor in tumor suppression, which has been implicated in many cellular processes; including telomere maintenance, recombination and damage repair, embryonic development and genomic stability." (PMID 32973865, 2020). "BRCA1 and BRCA2 are tumor suppressor genes, and defective tumors with loss of the copy of either gene are shown to be intrinsically sensitive to PARP inhibitors in both pre-clinical and clinical models." (PMID 32117762, 2020). "This RAD52 mutation causes a reduction in DSB repair by SSA, suggesting that defects in RAD52‐dependent DSB repair are linked to reduced tumor risk in BRCA2‐mutation carriers." (PMID 32175645, 2020). "The term “BRCAness” describes BRCA1 or BRCA2 mutation phenocopies, which represent the situation in which a tumor cell has an HRR obstruction with a germline BRCA1 or BRCA2 deficiency." (PMID 32122376, 2020). "The differentially classified samples included four non-BRCA1/2 tumours (FBC050798, FBC020636, FBC060411 and FBC070086) and one tumour from pathogenic BRCA2 mutation carrier (FBC013587)." (PMID 32818150, 2020). "Conversely, our results suggest that BRCA2 mutations are associated with a more aggressive PCa phenotype; the association was stronger for GS ≥ 7 than for GS ≤ 6 tumours." (PMID 31495749, 2020). "The p.Val859Ser*22 mutation of BRCA2, is likely pathogenic and the cause of tumor development, as it generates an early stop codon at position 881 of the BRCA2 protein and truncates proteins with deleterious activity." (PMID 33324554, 2020). "The original BRCA2 mutation was detected at a frequency of 83% using a separate ddPCR probe, confirming a high tumour content in the biopsy." (PMID 31577852, 2020). "The expression of all approximately 7500 probes was able to distinguish BRCA1-associated tumours from BRCA2-associated tumours." (PMID 33081408, 2020). "Tumor samples were obtained from 30 patients with pathogenic germline variants in BRCA2 (n = 25) and BRCA1 (n = 5), as well as from an additional 30 patients without pathogenic germline mutations." (PMID 33067557, 2020). "BRCA1 and BRCA2 are tumor suppressor genes that encode for proteins that maintain genomic stability through DNA repair." (PMID 32610620, 2020). "Two patients had pathogenic germline BRCA2 mutations; in both of these cases, both the primary untreated tumor and the mCRPC biopsy presented loss of heterozygosity resulting in biallelic BRCA2 loss." (PMID 31874108, 2020). "Due to the alteration of BRCA1 and BRCA2 proteins in tumor cells, BRCA-mutated cells are unable to properly repair double-strand breaks, classically induced by DNA-alkylating agents." (PMID 33302444, 2020). "In this study, we used Multiplicom BRCA MASTR Dx assay for the detection of BRCA1/BRCA2 variants using DNA extracted from FFPE tumor samples, for which it has CE-IVD marking." (PMID 32850417, 2020).
tumor (continued). "We profiled the available baseline tumor and progression blood samples using next-generation sequencing panel tests and identified polyclonal BRCA2 reversion mutations post carboplatin treatment but prior to rucaparib treatment." (PMID 32171277, 2020). "One (9.1%) of these test-ineligible women harbored a germline mutation in BRCA2, with tumor biomarkers reported as 10% ER, 1% PR, and 0+ HER2." (PMID 33302456, 2020). "For instance, tumor cells from carriers of both pathogenic BRCA2 mutations and hRAD52 S346X should have a reduced ability to survive when exposed to chemotherapy‐induced DSBs." (PMID 32175645, 2020). "The one tumor exhibiting genomic instability (IGR-07) harbored a loss of BRCA2, interpreted as heterozygous [log2 (ratio) = −0.4]." (PMID 32575483, 2020). "A total of 277 genes were differentially expressed between BRCA1 and BRCAx tumours, and 31 genes were differentially expressed between BRCA2 pathogenic variants and BRCAx tumours." (PMID 33081408, 2020). "RHPS4 has a stronger activity towards BRCA2 deficient tumours by increasing DNA damage that cannot be repaired by cells." (PMID 32098397, 2020). "One such mechanism is acquired BRCA2 reversion mutations, where previously BRCA-2-deficient tumor cells are able to achieve BRCA2 proficiency due to constant selection pressure of PARP inhibition." (PMID 32117762, 2020). "Genomic profiling of the available baseline tumor and progression blood samples using next-generation sequencing panel tests identified polyclonal BRCA2 reversion mutations post carboplatin treatment but prior to rucaparib treatment." (PMID 32171277, 2020). "In 2009, a phase I clinical trial of olaparib was started, including ovarian and breast tumor patients (among other tumor types included) with germline BRCA1 or BRCA2 mutations." (PMID 32005245, 2020). "This is the case with tumours associated with mutations in one copy of either BRCA1 or BRCA2; in these tumours, PARP1/2 inhibitors lead to an accumulation of DNA SSBs, which are converted during replication to irreparable toxic DNA double-strand breaks." (PMID 33050515, 2020). "The variant allele frequency of BRCA2 c.9294C>G was 57% in tumor tissue suggesting possible somatic copy number change at this locus." (PMID 32468491, 2020). "Compared to vehicle treatment, MMC treatment potently inhibited the in vivo growth of heterozygous BRCA2 monoallelic mutant SNU-1 tumor xenografts in immune-deficient mice (p < 0.01) and significantly improved the survival rate of the mice (p < 0.05)." (PMID 32980867, 2020). "This confirmed a significantly higher prevalence of MF/MC tumours amongst BRCA2 mutation carriers compared with BRCA1 mutation carriers." (PMID 32022473, 2020). "The specific mutation status of these cells represents a diagnostic and therapeutic target that on the one hand explains the consequences of BRCA2 deficiency but on the other hand can be used to therapeutically attack the tumor cells." (PMID 32005245, 2020). "Because error-free HR is impaired in BRCA1- and BRCA2-deficient cells, it is likely that error-prone repair of HR substrates are causal for the mutations observed in these tumours." (PMID 32680986, 2020). "The difference observed in the size of the gene lists suggested that BRCAx tumours are more similar to tumours from BRCA2 pathogenic variant carriers than BRCA1 pathogenic variant carriers." (PMID 33081408, 2020). "This case also potentially expands the constellation of neoplasms associated with germline BRCA2 mutation." (PMID 32571290, 2020). "The BRCA1 (chromosome 17q21) and BRCA2 (chromosome 13q12.3) are tumor suppressor genes that encode for proteins essential in DNA double strand break repair by homologous recombination (HR)." (PMID 33233347, 2020). "Based on the assumption that BRCA-like events would have similar downstream effects on tumor biology as BRCA1/BRCA2 germline mutations, we quantified these effects based on somatic-mutation signatures and gene-expression profiles." (PMID 32997669, 2020).